VAMP8 (vesicle associated membrane protein 8)
Description:
SNAREs (soluble N-ethylmaleimide-sensitive factor-attachment protein receptors) are essential proteins for intracellular membrane fusion. SNAREs localized on opposing membranes assemble to form a trans-SNARE complex, an extended, parallel four-helix bundle whose assembly releases energy that drives membrane fusion. The core SNARE complex typically consists of four alpha-helical domains, three from target membrane SNAREs (t-SNAREs) and one from a vesicle SNARE (v-SNARE). VAMP8 is a v-SNARE that forms a SNARE complex with the t-SNARE STX11 and SNAP23. This SNARE complex plays a critical role in the regulated exocytosis of cytotoxic granules by natural killer (NK) cells and cytotoxic T-lymphocytes. VAMP8 plays a role in autophagy where it controls organelle-organelle membrane fusion through a VAMP8, SNAP29 and STX17 SNARE complex that mediates the fusion of autophagosome and lysososome membranes. VAMP8 is required for dense-granule secretion in platelets. Also plays a role in regulated enzyme secretion in pancreatic acinar cells (By similarity). Involved in the abscission of the midbody during cell division, which leads to completely separate daughter cells (By similarity). Involved in the homotypic fusion of early and late endosomes (By similarity). Also participates in the activation of type I interferon antiviral response through a TRIM6-dependent mechanism.
Synonyms: VAMP-8; EDB
Tractability: Antibody: its Gene Ontology location is reachable by antibodies, with high confidence; UniProt places it where antibodies can reach, with medium confidence; UniProt predicts a signal peptide or a membrane-spanning region; the Human Protein Atlas places it where antibodies can reach. PROTAC: ubiquitination databases record sites on it; its protein half-life has been measured.
Gene: Protein-coding gene on chromosome 2 (85,561,562 to 85,582,031, forward strand). Ensembl gene ENSG00000118640.
Subcellular location: Lysosome membrane; Early endosome membrane; Late endosome membrane; Cell membrane; Zymogen granule membrane
Subcellular location (Human Protein Atlas): Golgi apparatus; Plasma membrane; Nucleoplasm
Pathways (Reactome):
Vesicle-mediated transport: Cargo recognition for clathrin-mediated endocytosis; Clathrin-mediated endocytosis; Golgi Associated Vesicle Biogenesis; Lysosome Vesicle Biogenesis; trans-Golgi Network Vesicle Budding
Immune System: ER-Phagosome pathway; Neutrophil degranulation
Gene Ontology:
Molecular function: chloride channel inhibitor activity; fusogenic activity; protein binding; SNAP receptor activity; syntaxin binding
Biological process: autophagosome maturation; autophagosome membrane docking; cytotoxic T cell degranulation; eosinophil degranulation; mucus secretion; negative regulation of secretion by cell; neutrophil degranulation; positive regulation of histamine secretion by mast cell; regulation of protein localization to plasma membrane; symbiont entry into host cell; vesicle fusion; cellular response to starvation; macroautophagy; SNARE complex assembly; protein-containing complex organization; vesicle-mediated transport
Cellular component: azurophil granule membrane; cytoplasm; cytosol; early endosome membrane; extracellular exosome; immunological synapse; late endosome membrane; lysosomal membrane; membrane; mucin granule; perinuclear region of cytoplasm; plasma membrane; recycling endosome; secretory granule membrane; SNARE complex; vesicle; autophagosome membrane; clathrin-coated endocytic vesicle membrane; early endosome; phagocytic vesicle membrane; recycling endosome membrane; specific granule membrane; tertiary granule membrane; zymogen granule membrane; endosome; and 1 more
Genetic constraint (gnomAD): Loss-of-function variants: 9 observed, 10.25 expected, observed/expected ratio (o/e) 0.88, 90% interval 0.53 to 1.52. The upper end of that interval is the gene's LOEUF score, 1.52, which puts it in group 6 of 6, group 1 being the genes least tolerant of losing a copy. Missense variants: 108 observed, 130.49 expected, observed/expected ratio (o/e) 0.83, 90% interval 0.71 to 0.97. Synonymous variants: 42 observed, 44.09 expected, observed/expected ratio (o/e) 0.95, 90% interval 0.74 to 1.23.
Homologues: Orthologues: macaque VAMP8 (100% identical), dog VAMP8 (94% identical), pig VAMP8 (91% identical), guinea pig VAMP8 (89% identical), mouse Vamp8 (87% identical), rat Vamp8 (86% identical), rabbit VAMP8 (83% identical), zebrafish vamp8 (62% identical), Caenorhabditis elegans vamp-8 (39% identical). Paralogues in human: VAMP7 (34% identical), VAMP1 (33% identical), VAMP3 (32% identical), VAMP2 (31% identical), VAMP4 (26% identical), VAMP5 (25% identical), YKT6 (22% identical), SEC22B (20% identical), SEC22A (15% identical), SEC22C (14% identical).
Diseases named in the same sentence as VAMP8 in open-access papers:
VAMP8 is named in the same sentence as 59 diseases in open-access papers, as found by Europe PMC text mining. Sharing a sentence is not in itself a finding about the gene and the disease. The quoted sentences say what the papers report.
glioma (11 papers, 2016 to 2025). A benign or malignant brain and spinal cord tumor that arises from glial cells (astrocytes, oligodendrocytes, ependymal cells). "Each one of the two correlation coefficients manifested that both SPP1 and HMOX1 were consistently co‐expressed with 20 genes in glioma samples, such as VAMP8, RAC2, MSR1, CAPG and FBP1." (PMID 40495644, 2025). "VAMP8 was found to be an oncoprotein by facilitating glioma cell growth and chemotherapy resistance to TMZ." (PMID 34645799, 2021). "VAMP8 is significantly overexpressed in human glioma specimens and can be used as a new indicator of glioma prognosis and treatment." (PMID 34804194, 2021). "Overexpression of VAMP8 has also been associated with resistance to temozolomide in human glioma cells, and knockdown of STX17 in glioma cells overexpressing VAMP8 led to increased chemosensitivity." (PMID 33718194, 2021). "In this context, it is noteworthy that VAMP8 was the most upregulated transcript in glioma T98G-GAB cells stably transfected with GLS227, while reduced VAMP8 levels have been associated to invasive phenotype in breast cancer cells." (PMID 32042057, 2020). "High expression of VAMP8 enhanced the cell proliferation of glioma and glioma growth by regulating cell cycle in the G0/G1 phase." (PMID 33384961, 2020). "Vesicle-associated membrane protein 8 (VAMP8), first identified as an endosomal SNARE, is significantly overexpressed in human glioma specimens and promotes cell proliferation." (PMID 26830677, 2016). "Furthermore, the role of LINC01426 in glioma has also received increasing attention, including sponging miR-345-3p and upregulating VAMP8 to promote glioblastoma." (PMID 36226186, 2022). "Taken together, these results showed that LINC01426 could competitively bind to miR345-3p and then elevate the mRNA of VAMP8 in glioma cells." (PMID 32699526, 2020). "We further found that miR345-3p target VAMP8, a oncogenic protein in gliomas and breast cancer, and the tumor suppressive roles could be sequestered by LINC01426." (PMID 32699526, 2020). "VAMP8 is a SNARE protein, which function as an oncogene by promoting cell proliferation and therapeutic resistance in glioma." (PMID 34880206, 2021). "Collectively, the function of these genes in tumors, especially VAMP8 and FCGR2A in gliomas, has been fully demonstrated." (PMID 34880206, 2021). "We found that knockdown of VAMP8 decreased TMZ resistance, similar to a previous study that showed that VAMP8 silencing could reduce TMZ resistance in glioma cells." (PMID 34645799, 2021). "Furthermore, VAMP8 contributes to TMZ resistance by elevating the autophagic level, while silencing of VAMP8 using siRNA could impair the autophagic flux and alleviate TMZ resistance in glioma cells." (PMID 26830677, 2016).
breast carcinoma (4 papers, 2010 to 2020). "Our data, indicating the likelihood that Rab17 exerts its anti-invasive effects by maintaining Vamp8 levels, prompted us to investigate the relationship between Vamp8 and invasive pathology in breast cancer." (PMID 28062852, 2017). "We, therefore, provoked breast cancer cell invasiveness by knocking down Rab17 or Vamp8 and tested the requirement for NRP2 in this." (PMID 28062852, 2017). "Next, we examined VAMP8 expression in breast cancer-derived cell lines and found that VAMP8 was expressed at low levels in a panel of breast cancer cells lines compared to expression levels in MCF10A cells." (PMID 21437235, 2011). "We then deployed a large tissue microarray (TMA) containing 542 human breast tumours to test whether this inverse relationship between Vamp8 levels and features of tumour aggressiveness could be observed in human breast cancer." (PMID 28062852, 2017). "Moreover, Vamp8 levels were significantly correlated with the breast cancer molecular subtype in a way that was consistent with tumour grade." (PMID 28062852, 2017). "Our identification of Vamp8 as an interactor of Rab17 and the fact that Vamp8 was downregulated in Rab17-depleted cells prompted us to determine whether Vamp8 contributes to the ability of Rab17 to function as a suppressor of breast cancer cell invasiveness." (PMID 28062852, 2017). "Most of the breast cancer cell lines we examined were insulin-independent for proliferation; the one exception being the SUM44 cell line, which expressed high VAMP8 levels and also required insulin." (PMID 21437235, 2011).
glioblastoma (4 papers, 2020 to 2022). The most malignant astrocytic tumor (WHO grade IV). "In addition, LINC01426 accelerates glioblastoma progression by regulating miR-345-3p/VAMP8 signaling axis." (PMID 34852770, 2021).
periodontitis (4 papers, 2021 to 2025). An acute or chronic inflammatory process that affects the tissues that surround and support the teeth. "Interestingly, several genes among the most significant differentially methylated genes that were part of the vesicle trafficking gene sets are known to interact with the genes VAMP3 and VAMP8, which are both suggestive risk genes of periodontitis." (PMID 34732256, 2021). "VAMP8 is involved in membrane vesicular trafficking and shares a molecular pathway that has been associated with both CAD and periodontitis." (PMID 40830908, 2025).
viral infection (4 papers, 2015 to 2025). "In addition, the recent identification of specific regulators of autophagosome maturation, such as syntaxin-17, SNAP29, and VAMP8, presents an exciting opportunity to further define the role of this critical autophagic process in limiting and/or enhancing viral infections." (PMID 25811485, 2015).
osteosarcoma (3 papers, 2020 to 2023). A usually aggressive malignant bone-forming mesenchymal neoplasm, predominantly affecting adolescents and young adults. "Previous study identified that high expression of VAMP8 was associated with oncogenesis and metastasis of osteosarcoma." (PMID 33384961, 2020). "Low levels of VAMP8 in osteosarcoma tissues were associated with patients’ poor prognosis." (PMID 37405957, 2023). "Collectively, our results indicate that VAMP8 inhibits the migratory and invasive capabilities of osteosarcoma cells." (PMID 37405957, 2023). "In conclusion, our study anticipated that VAMP8 inhibits osteosarcoma metastasis by promoting the proteasomal degradation of DDX5, consequently inhibiting WNT/β-catenin signaling and EMT." (PMID 37405957, 2023). "In this study, we observed a significant downregulation of VAMP8 in osteosarcoma cells and tissues." (PMID 37405957, 2023). "VAMP8 inhibited the migration and invasion capability of osteosarcoma cells." (PMID 37405957, 2023). "Additionally, VAMP8 promoted autophagy flux, which may contribute to the suppression of osteosarcoma metastasis." (PMID 37405957, 2023). "However, the specific functional role of VAMP8 in osteosarcoma progression remains unclear." (PMID 37405957, 2023). "Although seldom previous studies have revealed the expression and role of VAMP8, APOC1 and A2M in osteosarcoma, exploration in some other tumors has well proved that these genes are important tumor-related regulatory factors." (PMID 32665038, 2020). "Five of the seven immune-related genes (CDCA7, GZMA, SLC7A7, VAMP8, and EVI2B) were highly expressed in the osteosarcoma group, while two of these immune-related genes (IFITM3 and ACTA2) were lowly expressed." (PMID 33384961, 2020). "VAMP8, A2M, HLA-DRA, SPARCL1, HLA-DQA1, APOC1 and AQP1 were identified continuously upregulating during the oncogenesis and metastasis of osteosarcoma." (PMID 32665038, 2020). "The heatmap of these seven immune-related genes expression level in GSE42352 indicated that five of these genes (CDCA7, GZMA, SLC7A7, VAMP8, and EVI2B) were highly expressed in the osteosarcoma group, but two of these genes (IFITM3 and ACTA2) were highly expressed in the normal group." (PMID 33384961, 2020).
Sepsis (3 papers, 2021 to 2024). Sepsis is defined as life-threatening organ dysfunction caused by a dysregulated host response to infection. "ISE pretreatment diminished enhanced SNAP-23 and VAMP-8 protein expression in the platelets of CLP-induced sepsis mice (n = 5 independent experiments)." (PMID 38921594, 2024). "These co-expressed genes, along with VAMP8, suggest an intrinsic link between the kidneys and other organs, potentially explaining the multi-organ dysfunction observed in sepsis and the need for diverse clinical indicators for diagnosis." (PMID 39086896, 2024).
Sjögren’s syndrome (3 papers, 2017 to 2018). "Firstly, the chronic GVHD (cGVHD) and Sjögren's syndrome (SS)-impaired lacrimal gland (LG) tissue sections from humans for diagnostic purpose were evaluated for VAMP8 expression by histopathology and immunohistochemistry." (PMID 29098081, 2017). "While VAMP8 is expressed in the apical cytoplasm in healthy individuals, it is expressed in the entire cytoplasmic in patients with Sjögren’s syndrome." (PMID 30336591, 2018). "VAMP8 expression in the lacrimal glands is altered, from the apical to the basal side, in individuals with dry eyes; in Sjögren’s syndrome, the expression of the gene and protein is decreased in the acinar cells of labial salivary glands." (PMID 30336591, 2018). "In labial salivary glands from the patients with Sjögren’s syndrome, syntaxin-4 and VAMP-8 expression were decreased, whereas syntaxin-3 expression was increased." (PMID 29358308, 2018). "We reported that VAMP8 was abnormally expressed in the human lacrimal gland impaired by Sjögren's syndrome (SS)." (PMID 29098081, 2017).
atherosclerosis (2 papers, 2021 to 2022). A disease characterized by the build-up of fatty material and calcium deposition in the arterial wall resulting in partial or complete occlusion of the arterial lumen. "In 46 upregulated OCRGs in MDs, upregulation of two regulators VAMP8 and SERPINA1 was shared between obese and atherosclerosis; and two upregulated regulators DNM2 and MTFP1 were shared between T2D and atherosclerosis." (PMID 34368262, 2021). "Several risk markers related to the immune response that have key roles in atherosclerosis were identified, including the top aging marker MMP8, disease markers KIR3DL1 and MAGEA6, network markers based on degree (RBM10, PJA2, and CMTM6), and network markers based on betweenness (IRAK1 and VAMP8)." (PMID 35706446, 2022).
colitis (2 papers, 2019 to 2024). Inflammation of the colon. "Here the authors describe alterations in intestinal immune state and microbiota composition, as well as increased susceptibility to experimental colitis in mice deficient for VAMP8." (PMID 31541089, 2019). "Colitis was significantly worse in Vamp8−/− as assessed by shortening of the colon and splenomegaly." (PMID 31541089, 2019). "The late onset of moderate inflammation in the absence of Muc17 contrasted acute induction of severe colitis in C3GnT–/–, Vamp8–/–, and Tgm3–/– mice with defects in Muc2 glycosylation, secretion, and cross-linking." (PMID 39699961, 2024). "While we did not observe rampant inflammation basally or spontaneous colitis in Vamp8−/−, slight perturbation of the barrier had catastrophic effects." (PMID 31541089, 2019).
nasopharyngeal carcinoma (2 papers, 2024 to 2025). A carcinoma arising from the nasopharyngeal epithelium. "Integrating transcriptome‐wide association study, expression quantitative trait loci, and genome‐wide association study identifies rs1058588 at the vesicle‐associated membrane protein 8 (VAMP8) locus as a risk variant for nasopharyngeal carcinoma (NPC)." (PMID 39854120, 2025).
pancreatitis (2 papers, 2020 to 2022). Inflammation of the pancreas. "The acute inhibition of VAMP8-mediated secretion resulted in the intracellular accumulation of trypsin causing acinar cell damages during pancreatitis." (PMID 36313558, 2022). "Interestingly, analysis of Vamp8-deficient mice revealed a major physiological role for this protein in inflammatory conditions such as pancreatitis, as the Vamp8-/- mice showed a significantly attenuated inflammatory response compared to wild-type animals." (PMID 32823483, 2020).
allergic reaction (1 paper, 2023). "In a non-allergic reaction, degranulation is initiated by the fusion of granules with the plasma membrane, but this process depends on the interaction between vesicle-associated membrane protein 8 (VAMP8) and 7 (VAMP7) exclusively present on the granule membrane of the mast cell." (PMID 37629547, 2023).
Arterial thrombosis (1 paper, 2016). The formation of a blood clot inside an artery. "The clinical evidences suggest that vesicle-associated membrane protein 8 (VAMP8)/endobrevin, a critical v-SNARE involved in platelet granule secretion, may be associated with clinical arterial thrombosis." (PMID 28042196, 2016).
atopic dermatitis (1 paper, 2018). "Distinct subsets of mast cell granules could be selectively regulated by the N-terminal-mimicking peptides derived from VAMP2 and VAMP8, and they effectively decreased the symptoms of atopic dermatitis in mouse models." (PMID 29696021, 2018).
breast tumours (1 paper, 2017). "Furthermore, because some Vamp8 immunoreactivity observed in breast tumours appeared to be diffusely distributed within the cells, we scored our TMA only for Vamp8 that was localised to membranous structures that were either in the cell periphery or within the cell." (PMID 28062852, 2017).
Cerebral ischemia (1 paper, 2024). Restriction of arterial blood supply to the brain associated with insufficient oxygenation to support the metabolic requirements of the tissue. "This suggested that cerebral ischemia-inactivated NSF greatly suppressed reactivation of STX17 and VAMP8." (PMID 39155286, 2024).
chordoma (1 paper, 2014). Chordomas are rare malignant tumors arising from embryonic remnants of the notochord in axial skeleton. "We demonstrate the expression of new potential candidates for chordoma tumorigenesis, such as CD24, ECRG4, RARRES2, IGFBP2, RAP1, HAI2, RAB38, osteopontin, GalNAc-T3, VAMP8 and others." (PMID 24452533, 2014).
COVID-19 (1 paper, 2022). A disease caused by infection with severe acute respiratory syndrome coronavirus 2. "VAMP8 was consistently down-regulated in both infected and bystander BALF epithelial cells, with the expression level observed in infected cells from severe COVID-19 patients." (PMID 36661509, 2022).
ductal carcinoma in situ (1 paper, 2017). "Reduced levels of Vamp8 promote transition between ductal carcinoma in situ (DCIS) and a more invasive phenotype." (PMID 28062852, 2017).
infectious colitis (1 paper, 2019). A viral or bacterial infectious process affecting the large intestine. "Despite this, Vamp8−/− is highly susceptible to both chemical and infectious colitis demonstrating the fragility of the intestinal mucosa without proper mucus exocytosis mechanisms." (PMID 31541089, 2019).